TLR9 (toll like receptor 9)
Diseases named in the same sentence as TLR9 in open-access papers (continued):
Sharing a sentence is not in itself a finding about the gene and the disease.
hematoma (1 paper, 2022). A hematoma is a collection of blood from a vascular structure into an extravascular space. "Histological experiments showed that ODN1826‐induced TLR9 activation substantially promoted Iba‐1‐ and HO‐1‐positive cell numbers with an enlarged cell body size around the hematoma, which indicated the M/M activation effects of TLR9." (PMID 35876247, 2022). "In conclusion, our results demonstrate that post‐ICH TLR9 activation can enhance M/M activation and phagocytic function, which facilitates hematoma/iron clearance and reduces brain injury in mice." (PMID 35876247, 2022). "TLR9‐mediated protection was further evidenced by the fact that ODN1826‐treated mice exhibited faster hematoma resolution, less neural injury, and better functional outcomes than control mice after ICH." (PMID 35876247, 2022). "Post‐ICH, TLR9 activation facilitated M/M activation, enhanced M/M phagocytosis functions, and induced M/M polarization after ICH, which facilitated hematoma/iron clearance, alleviated neural injury, and improved functional recovery." (PMID 35876247, 2022). "However, whether TLR9 is upregulated in the central nervous system after ICH and plays a role in hematoma clearance and neurorecovery remains unknown." (PMID 35876247, 2022).
Hematuria (1 paper, 2014). The presence of blood in the urine. "In this study, tonsillar TLR9 expression was significantly higher in the IgAN patients with reduced hematuria and serum GdIgA1 levels, compared with patients not responding to tonsillectomy alone." (PMID 24586974, 2014).
hemophagocytic lymphohistiocytosis (1 paper, 2023). "In contrast, dysregulated but functional TLR9 mutants may develop hemophagocytic lymphohistiocytosis–like symptoms." (PMID 37555846, 2023).
hemophilia A (1 paper, 2020). The most common form of hemophilia characterized by spontaneous or prolonged hemorrhages due to factor VIII deficiency. "Specifically, in a cohort of 100 severe hemophilia A patients, the inhibitor-positive status was associated with dysfunctional activation of IDO1 in human CD11c+ APCs in response to the “environmental danger signal” CpG ODN acting as ligand for the Toll-like receptor 9 (TLR9)." (PMID 32351505, 2020).
histoplasmosis (1 paper, 2020). A disease caused by the fungus Histoplasma capsulatum. "In the histoplasmosis model, TLR7/TLR9-deficient animals show a more aggressive infection, exhibiting increased neutrophil recruitment, increased lung damage, colonization in the brain, and consequently increased death." (PMID 33194839, 2020).
hypersensitivity pneumonitis (1 paper, 2013). Hypersensitivity pneumonitis (HP) is a pulmonary disease with symptoms of dyspnea and cough resulting from the inhalation of an antigen to which the subject has been previously sensitized. "Although the TLR2-/- mice, (and to a lesser extent the TLR9-/- mice), had reduced alveolitis compared to the WT mice, the differences were not statistically significant." (PMID 24023674, 2013).
hypoadiponectinemia (1 paper, 2020). "TLR9’s role in hypoadiponectinemia has implications for insulin sensitive tissues throughout the body." (PMID 33584545, 2020).
Impaired glucose tolerance (1 paper, 2022). An abnormal resistance to glucose, i.e., a reduction in the ability to maintain glucose levels in the blood stream within normal limits following oral or intravenous administration of glucose. "TLR9 may lead to impaired glucose tolerance and islet dysfunction by affecting the glucose uptake in diabetic adipose tissue and the malignant induction of adipose tissue." (PMID 35187175, 2022).
infectious colitis (1 paper, 2025). A viral or bacterial infectious process affecting the large intestine. "TLR9 deficiency leads to bradykinin receptor upregulation in the colonic epithelium following infectious colitis, contributing to the development of PI-IBS." (PMID 41293152, 2025). "A previous clinical follow-up study suggested that TLR9 dysfunction is a potential mechanism involved in development PI-IBS, thus we sought to determine the role of TLR9 signaling in mice with and after resolution of infectious colitis." (PMID 41293152, 2025).
inflammatory skin disorders (1 paper, 2024). "Other genes, such as IL-21R, GSDMC, CCR7, TLR9, HAS1/3, IL-17A, IL-22, and CXCL10, have been previously identified as genes associated with various inflammatory skin disorders." (PMID 38612783, 2024).
inner ear disease (1 paper, 2017). "In addition, TLR9 has been confirmed to contribute to the recognition of auto-antigens and induce auto-immune inner ear disease with hearing loss, a specific complication of MD, thus validating its special role in MD." (PMID 28787010, 2017).
invasive breast carcinoma (1 paper, 2024). A carcinoma that infiltrates the breast parenchyma. "Overexpression of TLR9 was associated with the induction of epitheliomesenchymal transition (EMT) and deregulation of EGFR signaling in invasive breast carcinomas." (PMID 38850110, 2024).
Kaposi's sarcoma (1 paper, 2023). A malignant neoplasm characterized by a vascular proliferation which usually contains blunt endothelial cells. "One such example is a study between TLR9, HLA class I/II alleles, and a vaccine construct against Kaposi’s sarcoma, while another study on Candida auris vaccine design reported docking between TLR5 and MHC class-II HLA DRB_0101 with scores in a similar range." (PMID 38053576, 2023).
kidney injury (1 paper, 2023). Trauma to the kidney. "The dendritic cell surface receptor DEC205 is shown to facilitate the ligation of TLR9, the increased Th17 immune response and the development of kidney injury." (PMID 36674855, 2023).
Klebsiella Infections (1 paper, 2020). Infections with bacteria of the genus KLEBSIELLA. "TLR4, TLR2, and TLR9 signaling have been shown to play an important role in Klebsiella infection recognition and defense." (PMID 32670220, 2020).
laminopathy (1 paper, 2020). A rare genetic disorder caused by mutations in genes encoding proteins of the nuclear lamina. "In muscle tissue from laminopathy patients, TLR7 and TLR9 mRNA are significantly increased, and many muscle tissue-infiltrating CD68+ macrophages are TLR7 and TLR9 positive." (PMID 32580419, 2020).
leprosy (1 paper, 2021). Leprosy is a chronic infectious disease affecting primarily the skin and peripheral nervous system. "Recently, our group showed that bacterial histone-like protein (hlp) and human DNA were increased in patients with MB leprosy when B cells also had increased levels of TLR9 expression." (PMID 34621273, 2021).
leptospirosis (1 paper, 2014). A contagious bacterial infection caused by spirochetes of the genus Leptospira. "Aside from TLR2 and TLR4, other TLRs that have not yet been studied in the context of leptospirosis, such as TLR5 that senses flagellin, and TLR9, the receptor of bacterial DNA, could in theory be involved in the murine defense against L. interrogans." (PMID 24498450, 2014).
lymphoproliferative disorders (1 paper, 2017). "Therefore, the TLR9-MyD88-IRAK4 pathway is a potential therapeutic target to support disruption of EBV latency in EBV-associated lymphoproliferative disorders." (PMID 29088270, 2017).
malignant glioma (1 paper, 2022). A grade III or grade IV glioma arising from the central nervous system. "Immunotherapy with toll like receptor 9 (TLR9) agonist CpG ODN offers an emergent strategy to treat life‐threatening malignant glioma." (PMID 35253404, 2022).
marginal zone lymphoma (1 paper, 2018). A usually indolent mature B-cell lymphoma, arising from the marginal zone of lymphoid tissues. "Nevertheless, B cells from nodal marginal zone lymphomas did not expressed those markers in response to TLR9 stimulation." (PMID 29805758, 2018).
mastitis (1 paper, 2025). Inflammation of breast tissue during lactation or postpartum due to an obstructed duct or infection. "Levels of IFN-γ, IL-4, TNF-α, MYD88, CCL5, TLR4, TLR9, LTF, PRLR, Keap1 and OXSR1 genes expression were significantly up-regulated in ewes affected with mastitis than resistant ones." (PMID 40542007, 2025). "Mastitis-affected ewes had considerably higher levels of IFN-γ, IL-4, TNF-α, MYD88, CCL5, TLR4, TLR9, LTF, and PRLR gene expression than resistant ones." (PMID 40542007, 2025). "In the current investigation, qRT-PCR was used to measure the levels of antioxidant (CAT, GPX1, Keap1, OXSR1, ATOX1, GST, and Nrf2) and immune (IFN-γ, IL-4, TNF-α, MYD88, CCL5, TLR4, TLR9, LTF, and PRLR) genes in Barki ewes that were resistant and non-resistant to mastitis." (PMID 40542007, 2025).
meningococcemia (1 paper, 2012). "We identified TLR9 genotypes associated with protection against meningococcemia and enhanced local inflammatory responses inside the central nervous system, important steps in MM pathogenesis and defense." (PMID 22577991, 2012). "In this study, TLR9 -1237 and TLR9 +2824 mutant genotypes were associated with protection against meningococcemia, an essential prerequisite for meningeal invasion." (PMID 22577991, 2012). "We associated TLR9 SNPs with protection against meningococcemia, a prerequisite for meningeal invasion, and with elevated CSF leukocyte levels during MM." (PMID 22577991, 2012).
Merkel cell carcinoma (1 paper, 2022). "Although there are not many studies concerning the activation of TLR9 in polyomaviruses, it has been reported that in biopsies of patients with Merkel cell carcinoma there is decreased expression of TLR9." (PMID 35458396, 2022).
metastasis (1 paper, 2024). The spread or migration of cancer cells from one part of the body (where they first appeared) to another. "Consistent with our findings, the studied TLR9 rs187084 polymorphism was previously associated with advanced tumor stage and lymph node metastasis in NPC, another subgroup of HNSCC." (PMID 38850110, 2024).
microscopic polyangiitis (1 paper, 2023). Microscopic polyangiitis (MPA) is an inflammatory, necrotizing, systemic vasculitis that affects predominantly small vessels (i.e. small arteries, arterioles, capillaries, venules) in multiple organs. "Evidence of a strong association of TLR9 genotypes and haplotypes with GPA as well as a contrariwise association with microscopic polyangiitis was identified following genotyping of a large cohort of German AAV patients and further validated in Dutch and British cohorts." (PMID 36674855, 2023).
migraine (1 paper, 2024). "It highlights the cascade initiated by the binding of antiphospholipid antibodies (aPLs) to anionic phospholipids, the subsequent release of extracellular vesicles, and the activation of Toll-like receptors (TLR7 and TLR9), leading to neuroinflammation and migraine development." (PMID 39728754, 2024).
Miscarriage (1 paper, 2018). A pregnancy that ends at a stage in which the fetus is incapable of surviving on its own, defined as the spontaneous loss of a fetus before the 22th week of pregnancy. "Chi-squared test results showed that SNPs in TLR9 and IL-10 genes have statistically significant effect on the risk of miscarriage with highest of all genes' ORs of 13.23 and 12.86, respectively, for double-mutant genotypes." (PMID 30116270, 2018). "The following double genetic interactions showed statistically significant association with the risk of miscarriage: TLR9 and IL-6; TLR9 and IL-8; TLR9 and IL-10; and IL-10 and TLR4." (PMID 30116270, 2018). "The following triple genetic interaction showed statistically significant association with the risk of miscarriage: TLR9, IL-10, and TLR4." (PMID 30116270, 2018). "The multiple logistic regression analysis has also shown that the following double interactions showed statistically significant association with the risk of miscarriage: TLR9 and IL-10; TLR9 and IL-8; TLR9 and IL-6; and IL-10 and TLR4." (PMID 30116270, 2018). "TLR2, TLR4, IL-6, IL-8, and PGR SNPs can also affect the risk of miscarriage, but in less extent than TLR9 and IL-10." (PMID 30116270, 2018). "Moreover, one triple genetic interaction was significantly associated with the risk of miscarriage: TLR9, IL-10, and TLR4." (PMID 30116270, 2018). "Mutant SNPs in TLR9, IL-10, TLR2, IL-6, and IL-8 genes were found to have statistically significant effect on the risk of miscarriage with help of multiple logistic regression." (PMID 30116270, 2018). "TLR9 AA, IL-10 AA, and TLR4 CC interaction (z = 44.826, p < 0.001) and TLR9 GG, IL-10 CA, and TLR4 CT interaction (z = 44.826, p < 0.001) had a statistically significant positive effect on the risk of miscarriage." (PMID 30116270, 2018). "TLR9 GG and IL-10 CC interaction (z = −3.418, p=0.0006) and TLR9 GG and IL-10 CA interaction (z = −3.094, p=0.0019) had a statistically significant negative effect on the risk of miscarriage." (PMID 30116270, 2018).
MRSA pneumonia (1 paper, 2017). "Moreover, TLR9-mediated responses may serve as a means to augment antibacterial immunity in MRSA pneumonia or empyema, and these data may facilitate move forward in the development of new treatment strategies against MRSA infection." (PMID 28052108, 2017).
mycoplasma infection (1 paper, 2022). "Thus, the expression of this gene, which could be enhanced under mycoplasma infection, was also related to the suppression of TLR9." (PMID 36296238, 2022).
Myocardial fibrosis (1 paper, 2020). "Moreover, PSR staining showed that TLR9 knockout markedly reduced DOX‐induced myocardial fibrosis." (PMID 33140921, 2020).
necrotizing fasciitis (1 paper, 2012). "In a mouse necrotizing fasciitis model, the streptococcal DNase Sda1 suppressed TLR9-dependent INF-α and TNF-α induction." (PMID 22719247, 2012). "Similarly, in a murine necrotizing fasciitis model, IFN-α and TNF-α levels were significantly decreased in wild type mice infected with GAS expressing Sda1, whereas no such Sda1-dependent effect was seen in a TLR9-deficient background." (PMID 22719247, 2012).
oropharyngeal cancer (1 paper, 2021). Carcinoma, predominantly squamous cell, arising from the epithelial cells of the oropharynx. "The aim of the study was to assess TLR9 serum and tissue level in EBV(+) and EBV(−) oropharyngeal cancer patients." (PMID 34439137, 2021). "The aim of our study was to assess TLR9 level in patients with diagnosed oropharyngeal cancer with or without EBV infection." (PMID 34439137, 2021).
oropharyngeal squamous cell carcinoma (1 paper, 2023). "In HPV-associated oropharyngeal squamous cell carcinoma (OPSCC), TLR4 protein expression was lower while higher levels of TLR9 mRNA were observed." (PMID 37180114, 2023).
osteomyelitis (1 paper, 2022). An acute or chronic inflammation of the bone and its structures due to infection with pyogenic bacteria. "The dual loss of TLR2 and TLR9 alters callus formation and reduces trabecular bone loss during osteomyelitis." (PMID 36226943, 2022). "Overall, this study shows that, despite the clear role of TLR ligation in governing osteoclast differentiation in cell culture, TLR2 and TLR9 signaling contributes only modestly to inflammatory bone loss during S. aureus osteomyelitis." (PMID 36226943, 2022). "Therefore, we next sought to determine the impact of the dual loss of TLR2 and TLR9 on the pathogenesis of S. aureus osteomyelitis." (PMID 36226943, 2022). "In this study, we sought to determine how two PRRs capable of sensing staphylococcal PAMPs, TLR2 and TLR9, contribute to the control of the bacterial burdens and the dysregulation of bone homeostasis in the specific context of post-traumatic osteomyelitis." (PMID 36226943, 2022). "Thus, it is possible that TLR2 and TLR9 alter osteoblast activity during osteomyelitis by modulating the elaboration of IL-1 cytokines." (PMID 36226943, 2022). "We first assessed whether Tlr9−/− mice had any defects in their ability to control bacterial burdens during osteomyelitis." (PMID 36226943, 2022). "Because the loss of TLR2 and TLR9 did not alter the control of bacterial burdens, other innate immune pathways may be more influential in promoting host responses to osteomyelitis." (PMID 36226943, 2022). "Taken alongside data showing that TLR2- and TLR9-deficient osteoclast precursors undergo osteoclastogenesis upon intracellular infection with S. aureus, these data suggest that TLR2- and TLR9-independent pathways have the potential to modulate osteoclastogenesis during osteomyelitis." (PMID 36226943, 2022). "The dual loss of TLR2 and TLR9 does not compromise bacterial burden control during osteomyelitis." (PMID 36226943, 2022). "Therefore, we tested the hypothesis that compensation between TLR2 and TLR9 contributes to osteomyelitis pathogenesis." (PMID 36226943, 2022). "Our results demonstrate that neither TLR2 nor TLR9 significantly contributes to the host control of bacterial burdens in our model of post-traumatic osteomyelitis, suggesting that other pathways may play more prominent roles in constraining S. aureus infections in bone." (PMID 36226943, 2022).
otitis media (1 paper, 2024). Inflammation of the anatomical structures of the middle ear, which is most often caused by an infectious process. "HGMB1 and TLR9 have both been previously identified as involved in otitis media caused by NTHi." (PMID 38990812, 2024).
pancreatic adenocarcinoma (1 paper, 2020). "Lipopolysaccharide (LPS) can bind to the Toll-like (TLR) receptors; TLR2, TLR4, and TLR9 are associated with pancreatic adenocarcinoma development." (PMID 32344895, 2020). "In addition, TLR2, TLR4, and TLR9 and the downstream target of TLR4, MyD88, are associated with pancreatic adenocarcinoma development." (PMID 32344895, 2020).
peripheral nerve injury (1 paper, 2023). Injury to a peripheral nerve. "Previous studies indicate that activation of sNAMs in the sensory ganglia, after peripheral nerve injury, depends on downstream signaling generated by the activation of TLR2, TLR4, and TLR9." (PMID 37254842, 2023).
plasmacytoma (1 paper, 2022). Plasmacytoma is a localized mass of neoplastic monoclonal plasma cells that represents approximately 5% of all plasma cell neoplasms. "We therefore analyzed the role of these cytokines in TLR9-mediated prevention of early plasmacytoma development by treating mice with the neutralizing F3 anti-IFN-γ mAb and a specific anti-IL-12 mAb recognizing the heterodimeric cytokine (MM12A1.6)." (PMID 36714124, 2022). "To determine whether these cells were also involved in TLR9-mediated plasmacytoma growth prevention, we treated mice with a polyclonal anti-ASGM1 antibody." (PMID 36714124, 2022). "Interestingly, TLR9, in addition to viral DNA, recognizes hemozoin that is produced during infection by Plasmodium parasites and these parasites trigger enhanced prevention of early plasmacytoma growth in mice (manuscript in preparation)." (PMID 36714124, 2022).
prediabetes (1 paper, 2019). "Out of all the TLRs tested, IL-33 was directly correlated with TLR3 and TLR9 in individuals with T2D and prediabetes, respectively." (PMID 31073344, 2019). "Interestingly, IL-33 was directly correlated with TLR9 (r = 0.6; P = 0.002; n = 23) in individuals with prediabetes; and comparative analysis confirmed that higher levels of IL-33 were associated with significantly higher TLR9 expression (P = 0.003; median 8.84, n = 15 vs. median 4.6, n = 8)." (PMID 31073344, 2019).
prostate (1 paper, 2024). "Here, we utilized the class B synthetic agonist CPG-1668 to provoke a TLR9-mediated systemic immune response and demonstrate a significant impairment of prostate tumorigenesis." (PMID 38201300, 2024).
psychosis (1 paper, 2013). "Interestingly, increased peripheral responses of TLR2, TLR4, TLR8, and TLR9 have been detected in psychosis while TLR9 is associated with posttraumatic anxiety." (PMID 23843682, 2013).